IGF2BP1 (insulin like growth factor 2 mRNA binding protein 1)
Diseases named in the same sentence as IGF2BP1 in open-access papers (continued):
Sharing a sentence is not in itself a finding about the gene and the disease.
tumor (continued). "LINC01093 impedes GLI1 mRNA from binding to IGF2BP1 by competitive binding to IGF2BP1, thereby inhibiting the expression of GLI1 downstream genes and playing a crucial role in restraining tumor proliferation and metastasis." (PMID 38166832, 2024). "Our study shows that ZDHHC1, acting as a tumor suppressor gene, inhibits the growth of CRC cells and downregulates the expression of LIPG through palmitoylation of IGF2BP1." (PMID 39069526, 2024). "The m6A reader IGF2BP1 stabilizes the EP300 and MYC mRNAs by recognizing m6A modifications, forming a positive feedback loop that enhances tumor stemness and ultimately contributes to PDAC resistance." (PMID 39488785, 2024). "Studies have shown that IGF2BP1 can regulate the stability of mRNA (including PTEN, ACTB, MAPK4, MKI67, c-MYC, and CD44 to affect tumor proliferation, migration, and invasion." (PMID 37137887, 2023). "The tumor samples of PR-negative (P < 0.001), ER-negative (P < 0.001), or HER2-positive (P < 0.001) also possessed higher IGF2BP1 levels." (PMID 36966311, 2023). "Scholars have proven that IGF2BP1 can upregulate serum response factor (SRF) expression by a m6A-mediated decrease in mRNA decay, thereby enhancing tumor cell proliferation and invasion." (PMID 37304234, 2023). "In this context, a potentially tumor-driving interaction between circFAM13B and the RBP IGF2BP1 was revealed." (PMID 37835380, 2023). "Thus, the critical role of IGF2BP1 might promote this tumor progression." (PMID 36691477, 2023). "The elevated anti-tumour ability of CD8+ T cells and the increased immunotherapy sensitivity of BCa induced by circFAM13B were also weakened by IGF2BP1 transfection." (PMID 36747239, 2023). "The authors then linked IGF2BP1 with the M1 cell line by downregulating this protein, which resulted in reduced metastatic potential following xenografting of the mouse model with these cells and increased the survival of these mice (but did not affect tumour growth)." (PMID 37887559, 2023). "IGF2BP1 is specifically expressed in ETV6::RUNX1 positive B-ALL cell lines and its knockout reduces tumor cell proliferation and prednisolone resistance in Reh cell line." (PMID 37670323, 2023). "As a binding protein of the same type, IGF2BP1, IGF2BP2 and IGF2BP3 interact with same LncRNAs in the same tumor and has the same function." (PMID 37365581, 2023). "The TCGA database was used to identify expression patterns of IGF2BPs and showed that in PTC tumor samples IGF2BP3 were expressed in low levels while IGFBP2 was highly expressed, IGF2BP1 has barely any difference, compared to normal samples." (PMID 38092752, 2023). "Mechanistically, IGF2BP1 recognized the m6A modified sites on LDHA mRNA and enhanced its mRNA stability, thereby accelerating tumor energy metabolism." (PMID 36691477, 2023). "IGF2BP1, also known as IMP-1, CRD-BP and VICKZ1, is an oncofetal RNA-binding protein regulating tumor and stem cell fate." (PMID 37515119, 2023). "Like observed for BRDi, IGF2BP1-KO reduced EC50 values (~ threefold) for BIRC5i by YM-155, which was well tolerated in clinical trials and showed anti-tumor activity in combination therapy." (PMID 37246217, 2023). "Further analysis shows significant differences between the expression profiles of IGF2BP1 between KIRC, KIRP, and KICH tumor types cells with an ANOVA F-test with a value of p = 6.615 × 10−18." (PMID 37189628, 2023). "The expression patterns of IGF2BP1 and IGF2BP3 can be described as “cancerous embryos”, as they are largely absent in adult tissues but are severely upregulated in various tumors and tumor-derived cells." (PMID 36237306, 2022). "IGF2BP1 promotes SRF expression in an m6A dependent manner, enhances SRF dependent transcriptional activity at the post-transcriptional level, and promotes tumor cell proliferation and invasion." (PMID 35022030, 2022). "Meanwhile, compared with IGF2BP1 and IGF2BP3, IGF2BP2 expression exhibited striking intra- and inter-tumor heterogeneity." (PMID 36686749, 2022).
tumor (continued). "The correlation between IGF2BP1 and immune infiltrates in LUAD was investigated via CIBERSORT and Tumor Immune Estimation Resource (TIMER)." (PMID 35154270, 2022). "The RMPs upregulated in tumours or showing a positive correlation with poor outcomes usually gained more CNVs, such as ADAR, CPSF1, IGF2BP1, and YTHDF1." (PMID 36118888, 2022). "Of the six genes (IGF2BP1, GPRC6A, IL37, CRCT1, SEMG1, and PSG7) for which we analyzed the differential expression between tumor tissues and healthy tissues in TCGA, four genes (CRCT1, PSG7, IL37, and IGF2BP1) showed notable differences." (PMID 36276966, 2022). "Yellow background indicated the most significant (p < 0.0001) genes up-regulated in tumor tissues, including HNRNPC, YTHDF1, IGF2BP1, YTHDF2, RBM15, and IGF2BP3." (PMID 35581263, 2022). "Taken together, these results indicate an important regulatory impact of IGF2BP1 on the epigenetic landscape of NEN cells, thereby significantly affecting cell cycle progression and tumor cell viability." (PMID 35565249, 2022). "We also found that IGF2BP1 expression was significantly upregulated in HCC tissue and cell lines and positively correlated with tumor stage and OS." (PMID 33051595, 2021). "Further, this modification is coupled with the MEK1 kinase activity to activate ERK1/2 phosphorylation, leading to the upregulated expression of IGF2BP1 and its downstream target SOX2 and thus driving EC tumor progress." (PMID 33747724, 2021). "IGF2BP1 deletion disrupts with SRF/TCF- and SRF/MRTF-dependent transcriptional regulation in tumour cells through decreasing the richness of intracellular SRF." (PMID 34794452, 2021). "Differential expression analysis for these 24 m6A-related genes revealed that only IGF2BP1 and IGF2BP3 were highly expressed (|log2FoldChange| > 1, P<0.05) in SC tumor tissues relative to the normal group." (PMID 34621671, 2021). "Specifically, YTHDF1, IGF2BP2, KIAA1429, RBM15, IGF2BP1, ZC3H13, and METTL3 were significantly up-regulated in tumor tissues by unpaired T-tests (P < 0.05), while ALKBH5, YTHDC2, and METTL14 were significantly down-regulated (P < 0.01)." (PMID 34149792, 2021). "Different families of RBPs are dysregulated in cancer such as the family of the insulin-like growth factor 2 mRNA binding proteins (IGF2BPs), which includes the paralogues IGF2BP1, IGF2BP2 and IGF2BP3 and plays an oncogenic role in different tumor models." (PMID 33673232, 2021). "At the post-transcriptional level, IGF2BP1 maintains the expression of multiple SRF target genes, including PDZ and LIM domain 7 (PDLIM7) and forkhead box K1 (FOXK1), which further enhances tumor cell growth and invasion." (PMID 34692544, 2021). "Consistent with the transcriptome data, the protein expression of 4 genes (IGF2BP1, IGF2BP3, HMMR and ADAMTS12) were up-regulated in LUAD tumor samples." (PMID 34721973, 2021). "Regarding tumor stemness, in this study, YTHDF2, HNRNPA2B1, HNRNPC, IGF2BP1, and KIAA1429 were positively correlated with tumor stemness, while FTO was negatively correlated with tumor stemness." (PMID 35003079, 2021). "It appeared that IGF2BP1/3, ELAVL1, HNRNPA2B1, HNRNPC, KIAA1429, RBM15, LRPPRC, FMR1, YTHDF1/2 are highly expressed in the tumor while FTO, METTL14/16, WTAP, YTHDC1 and ZC3H13 are down-regulated." (PMID 35095993, 2021). "Therefore, we believe that the high expression of IGF2BPs may be one of the factors leading to the occurrence and development of LUAD in patients, and further study of the mechanism of IGF2BP1 in malignant tumors may be expected to provide a new method for tumor-targeted therapy." (PMID 34206803, 2021). "To explore the molecular mechanism by which IGF2BP1 accelerates the cell cycle and increases tumor cell proliferation, we first performed RIP to identify mRNAs which interact with IGF2BP1." (PMID 33391523, 2021).
tumor (continued). "Knockdown of IGF2BP1 expression level via applying a CRISPR/Cas9 genome editing system leading to upregulation of miR-4500 in GBM cells, and thereby suppressing tumor cell growth and metastasis to a large extent." (PMID 33768092, 2021). "One pro-tumorigenic mechanism of hsa-miR-372 is through de-repression of the tumor suppressor LATS2, while repression of IGF2BP1 by hsa-miR-372 is a tumor-suppressive mechanism." (PMID 34600545, 2021). "Early reports described IGF2BP1 as an RBP, involved in the regulation of mRNA and affecting tumor cell functions." (PMID 33391523, 2021). "Enhanced translation of IGF2 and IGF1R occurs via the de novo expression of the oncofetal RNA-binding proteins IGF2BPs (IGF2BP1, IGF2BP2, IGF2BP3) in different tumor types." (PMID 34440844, 2021). "The expression of m6A regulators with CNV amplification was significantly increased in CC samples compared to normal control samples, such as HNRNPA2B1, IGF2BP1, KIAA1429, and YTHDF1, while METTL14 and YTHDC2 were markedly decreased in the tumor specimens." (PMID 33500720, 2021). "The higher expression of YTHDF1, HNRNPC, IGF2BP1, VIRMA, and HNRNPA2B1, the more characteristics of tumor OV stem cells and the lower the tumor OV differentiation." (PMID 34150845, 2021). "IGF2BP1 was increased in MNA tumours, whereas in 4S disease (the possibly tumour suppressive) IGF2BP2 was the most up-regulated family member." (PMID 32707690, 2020). "To further understand the biology of the three genes, we analyzed the protein expression of IGF2BP1, VIRMA and ZC3H13 in OC in the Clinical Proteomic Tumor Analysis Consortium (CPTAC) samples." (PMID 32950970, 2020). "Intriguingly, IGF2BP1, LIN28B, and HMGA2 form a self-promoting network antagonizing the tumor-suppressive actions of the let-7 miRNA family." (PMID 32545414, 2020). "For example, IGF2BP1 can prevent the degradation of PTEN mRNA and promote the targeted migration of tumor cells." (PMID 32653017, 2020). "Particularly, in contrast to their low CNV frequencies (< 5%) in normal samples, CBLL1, METTL14, RBM15, IGF2BP1, YTHDC1, and YTHDF2 exhibited more than 20% difference in their frequencies of CNVs between tumor and normal samples." (PMID 33585234, 2020). "The regulation of SRF-dependent transcription by IGF2BP1 in cancer cells and the partial ‘phenocopy’ observed upon IGF2BP1 and SRF depletion in ES-2 cells suggested that both factors synergize in promoting a pro-proliferative and invasive tumor cell phenotype." (PMID 30371874, 2019). "IGF-II mRNA binding protein 1 (IGF2BP1), which participates in the Wnt/β-catenin pathway, is a target of miR-372 in the RCC cell lines, thus miR-372 acts as a tumor suppressor." (PMID 31110513, 2019). "In summary, these findings demonstrate that IGF2BP1 promotes SRF-dependent transcriptional regulation and that both factors likely synergize in promoting an ‘aggressive’ tumor cell phenotype." (PMID 30371874, 2019). "Although the study of IGF2BP1 in osteosarcoma (OS) is little, the observation of the restoration of miR-150 expression in OS cells could suppress the proliferation, migration and invasion, and growth of tumor cell and induce apoptosis by targeting it was reported." (PMID 29954406, 2018). "Recently, we reported that the insulin-like growth factor 2 mRNA-binding protein 1 (IGF2BP1) is overexpressed in both ERMS and ARMS patient-derived cell lines and in primary RMS tumours." (PMID 27966453, 2017). "Despite the heterogeneity of these cancers, we previously reported that the overexpression of two proteins, IGF2BP1 and cIAP1, occurs in all RMS patient-derived cell lines tested and in 75% of primary tumours." (PMID 27966453, 2017). "Taken together, our observations suggested that miR-9 plays a tumor suppressor role in HCC, partially via targeting IGF2BP1 to inhibit ERK and AKT oncogenic pathways." (PMID 26547929, 2015). "Among all genes tested, ONECUT2, IGF2BP1, and ANXA2 were aberrantly upregulated in tumor tissues compared to non-tumor tissues." (PMID 26547929, 2015).
tumor (continued). "The RNA level of IGF2BP1 (IMP-1), a stress-responsive regulator of mRNA stability, is highly upregulated in the tumor compared to muscle as well as bone." (PMID 25861239, 2015). "Of note, the RNA level of IGF2BP1 (IMP-1, CRD-BP, and ZBP-1) is highly upregulated in the tumor compared to muscle as well as bone." (PMID 25861239, 2015). "More interestingly, the expression of IGF2BP1 was positively correlated with the level of AFP, the most widely recognized tumor marker for HCC." (PMID 26547929, 2015). "Together, this suggests a fundamental role of IGF2BP1 and potentially IGF2BP3 in tumor cell dissemination, which presumably is observed in a broad variety of tumors." (PMID 23677615, 2013). "In vitro, IGF2BP1 was identified as a pro-migratory RBP, which in various tumor-derived cells promotes both the velocity and directionality of migration." (PMID 23677615, 2013). "We expect that such analyses will indicate IGF2BP1 and IGF2BP3 as useful biomarkers for evaluating tumor aggressiveness and will reveal avenues to pursue analyzing their suitability for targeted therapy." (PMID 23677615, 2013). "In contrast, the oncogene IGF2BP1-3 (IMP3, ↑8.793 fold) was highly over expressed in tumor relative to NB." (PMID 22280838, 2012). "Let-7a target genes relevant to transformation and subsequent tumor development include RAS, MYC, IGF2BP1 and HMGA2." (PMID 21853155, 2011). "IGF2BP1 increases SRF expression in an m6A-dependent manner by preventing SRF mRNA degradation by miRNAs and sustaining PDLIM7 and FOXK1 levels, thereby promoting tumour cell proliferation and invasion in OC." (PMID 40356909, 2025). "THOR contributed to cancer progression by interacting with IGF2BP1 (insulin-like growth factor 2 mRNA-binding protein 1); conversely, THOR silencing in cSCC cells induced the downregulation of IGF2BP1 mRNA and the inhibition of tumor progression." (PMID 40725772, 2025). "Subsequently, the IGF2BP1/LDHA axis can enhance glucose metabolism, thereby allowing tumor cells to better withstand hyperthermia, diminishing the cytotoxic impact of hyperthermia, and consequently leading to the development of hyperthermia resistance in CRC cells." (PMID 40584294, 2025). "Recent studies have found that IGF2BP1 can enhance the expression of MYC, a vital oncogene highly expressed in cancers, by promoting m6A methylation-mediated mRNA stability, thereby accelerating tumor cell growth." (PMID 40584294, 2025). "Furthermore, high MCMBP expression correlates with elevated levels of m6A “readers” (IGF2BP1, IGF2BP3) and “writers” (VIRMA, YTHDF3), a state thought to promote tumor progression by enhancing the stability and translation of oncogenic mRNAs." (PMID 41346611, 2025). "The Venn diagram shows that the expression levels of insulin-like growth factor 2 mRNA binding protein 1 (IGF2BP1), IGF2BP2 and insulin-like growth factor 2 mRNA binding protein 3 (IGF2BP3) were elevated in the tumor microarray data of HBL, and these genes were included in the m6A-related gene list." (PMID 40507253, 2025). "We found that IGF2BP1 and MDM2 protein levels correlated in cytokeratin-positive tumor cells." (PMID 41444249, 2025). "Despite its potential as an anti-tumor drug reported in several studies using preclinical models, there is no report regarding the use of IGF2BP1 inhibitor in clinical and/or clinical trials currently." (PMID 40584294, 2025). "MSI analysis of an HGSC-TMA confirmed a significant correlation of IGF2BP1 protein with PD-L1 protein expression in tumor cells, but not in T cells." (PMID 41444249, 2025). "Additionally, the expression of most of the regulators influences the tumor T feature of KIRC, LIHC, PRAD, STAD and THCA, especially IGF2BP1 in BRCA; IGF2BP2, IGF2BP3, LRPPRC, and METTL14 in KIRC; and IGF2BP3 in KIRP." (PMID 39457524, 2024).
tumor (continued). "When only tumor samples are included, the correlation analysis based on tumor samples still shows significant positive correlations between GAPDH protein expression and IGF2BP1 (r = 0.455, p < 0.001)." (PMID 38928396, 2024). "On day 21, the tumor volume of IGF2BP1/OE-CDC5L/KD NCI-H929 cells (302.18 ± 39.80 mm3) was significantly smaller than IGF2BP1/OE-CDC5L/NC cells (1465.70 ± 157.47 mm3; P < 0.001) and IGF2BP1/NC-CDC5L/NC cells (976.33 ± 114.00 mm3; P < 0.001)." (PMID 39534570, 2024). "IGF2BPs, generally including IGF2BP1, IGF2BP2 and IGF2BP3, have also been identified as m6A methyl-binding proteins and they are involved in the stability and degradation of various LncRNAs during the tumor occurrence and development." (PMID 37365581, 2023). "IGF2BP1 mRNA levels were significantly higher in BC tissues than in nearby noncancerous tissues and were positively correlated with tumour size and advanced clinical stages of BC." (PMID 37284313, 2023). "Additionally, inhibitors against FTO, ALKBH5, IGF2BP1, and ADAR1 have shown promising anti-tumor properties in vitro and in vivo." (PMID 38071304, 2023). "The mRNA expression levels of YTHDC2, YTHDF1, YTHDF3, IGF2BP1, and IGF2BP3 were significantly increased in tumour tissues compared with paired normal breast tissues, while the METTL14, WTAP, FTO, and IGF2BP2 expression levels were significantly decreased in tumour tissues." (PMID 36632454, 2023). "Knockdown of IGF2BP1 inhibited ESCC cell invasion and migration as well as tumor metastasis." (PMID 37644505, 2023). "Notably, we observed distinct differences in tumor weight and volume among the control group, the BIRC5 knockdown group, and the group with BIRC5 knockdown combined with IGF2BP1 overexpression." (PMID 38112021, 2023). "Apart from the roles in neoplastic diseases, IGF2BP1 is also involved in several nonneoplastic conditions." (PMID 36632449, 2023). "The importance of the Igf2bp1-cMyc mRNA interaction in tumorigenesis, however, remains to be determined, given that cMyc RNA is not upregulated in tumours induced by Igf2bp1 overexpression in the mammary glands of mice." (PMID 34895045, 2022). "Importantly, c-MYC is considered as a critical target of IGF2BPs, and lncRNAs recruits or binds to IGF2BP1 to stabilize or increase the mRNA of c-MYC, depending m6A modification in tumor progression." (PMID 35541906, 2022). "The m6A reader IGF2BP1 could stabilize the degradation of SOX2 mRNA in EC, thereby promoting tumor progression." (PMID 36371254, 2022). "In terms of methylation, the expression level of ECE2 was significantly negatively correlated with HNRNPC, IGF2BP1, IGF2BP3 and RBM15, which may affect the tumor progression of LUAD by affecting the m6A methylation level." (PMID 36299451, 2022). "Surprisingly, upon IGF2BP1 knock-down we also identified decreased mRNA levels of several epigenetic modifiers of the PRC2 complex, known to play an important role in the regulation of cell cycle and tumor cell proliferation." (PMID 35565249, 2022). "Furthermore, the tumor volume and weight were significantly reduced in the XCT-790 and sh-IGF2BP1 group compared with the XCT-790 or sh-IGF2BP1 groups alone." (PMID 35918761, 2022). "The suppression of IGF2BP1 did not inhibit primary tumor formation, but lung metastasis has been significantly inhibited." (PMID 35935853, 2022). "IGF2BP1 could recognize m6A modification and impair the miRNA-dependent downregulation of SRF expression, resulting in tumor cell growth and invasion." (PMID 34226535, 2021). "High IGF2BP1 expression was significantly associated with poor clinicopathological characteristics, including tumor size, advanced TNM stage, and poor differentiation, indicating that IGF2BP1 may have a critical function in HCC." (PMID 34779401, 2021). "IGF2BP1 and SRF exert synergistic effects in promoting tumour invasiveness." (PMID 34794452, 2021).